LGALS3 (galectin 3)
Diseases named in the same sentence as LGALS3 in open-access papers (continued):
Sharing a sentence is not in itself a finding about the gene and the disease.
testicular seminoma (1 paper, 2023). A malignant germ cell tumor arising from the testis. "The aim of the study is the immunohistochemical identification and evaluation of the expression of E-cadherin, B-catenin and galectin-3 in human testicular seminoma." (PMID 38144531, 2023). "In summary, our study showed significant differences in the immunoreactivity and expression of the assessed factors: β-catenin, E-cadherin and galectin-3 in testicular seminoma compared to control material." (PMID 38144531, 2023).
thymus (1 paper, 2018). "Besides, the direct effects of galectin-3 absence, such as defective intrathymic thymocyte migration, impaired proliferation and increased susceptibility to apoptosis, must be considered in the scenario of thymus atrophy observed in Gal-3−/−mice." (PMID 30042731, 2018). "From our new data, we suggest that both the increased GC contents and the lack of galectin-3 are likely to contribute to thymus atrophy in Gal-3−/− mice." (PMID 30042731, 2018).
tongue tumors (1 paper, 2021). "It is already known that Galectin-3 increases proliferation of breast, prostate, pancreatic, and tongue tumors." (PMID 34900729, 2021).
tubular carcinoma (1 paper, 2010). "The galectin-3 level was significantly higher in the primary tumor compared to adjacent normal tissue in 55% of the well-differentiated tubular carcinoma cases and in 50% of stage III and IV tumors." (PMID 23658855, 2010).
Umbilical hernia (1 paper, 2020). Protrusion of abdominal contents through a defect in the abdominal wall musculature around the umbilicus. "The results pointed out ACAN, MMPs, COLs, EPYC, VIT, CCBE1 and LGALS3 as strong candidates to trigger umbilical hernias in pigs since they act in the extracellular matrix remodeling and in the production, integrity and resistance of the collagen." (PMID 32379844, 2020). "Besides harboring a QTL region for umbilical hernia, LGALS3 differential expression profile was confirmed by the qPCR methodology." (PMID 32379844, 2020).
uremia (1 paper, 2024). A clinical syndrome associated with the retention of renal waste products or uremic toxins in the blood. "Our data showed that the higher the level of serum galectin-3, the more severe the degree of AoAC, providing clinical evidence that galectin-3 may play a role in VC in uremia." (PMID 38195853, 2024).
urolithiasis (1 paper, 2019). Stone(s) within the urinary tract. "Thus, it is thought that the polyLacNAc structure on mucin type O-glycosylated uFL-OPN in urinary stone forming urolithiasis patients could be reacted with endogenous lectins such as galectin 3 and might be have various direct or indirect biological functions." (PMID 31877766, 2019).
VEXAS syndrome (1 paper, 2024). An adult-onset inflammatory disease that affects only males and is caused by somatic, not germline, mutations. "Unsupervised principal components analysis (PCA) separated patients with VEXAS syndrome from the other groups on dimension 2, driven by inflammatory cytokines (IL-6, IL-18), IL-1 receptor antagonist (IL-1RA) and myelomonocytic markers (calprotectin and galectin-3)." (PMID 38291039, 2024).
tumor (742 papers, 1999 to 2026). "Although LGALS3, which encodes Galectin-3 (Gal-3), has been implicated in tumor biology, its precise role and regulatory mechanism in CRC remain incompletely understood." (PMID 42093989, 2026). "The first niche is a necrosis-lined core enriched for C1QC+/LGALS3+ tumour-associated macrophages whose transcriptome aligns with an M2-polarised, lipid-metabolising state." (PMID 40740859, 2025). "Higher galectin-3 expression in cancer and in circulation is associated often with tumour aggressiveness and poorer patient outcomes." (PMID 41023585, 2025). "LGALS3, a member of the galectin family, has been reported to be closely associated with tumor occurrence and development." (PMID 39794359, 2025). "The loss of parafibromin and galectin-3 expression has been linked with tumor aggressiveness and recurrence risk." (PMID 40142758, 2025). "Third, while our study demonstrates robust associations between LGALS3 expression, tumor biology, and patient outcomes, causality remains to be fully established." (PMID 41153387, 2025). "For example, conserved Gpnmb RecAM genes (e.g., Cd63, Fabp5, Lgals3, and Gpnmb) are hallmarks of lipid-associated macrophages found in the tumor microenvironment and chronically inflamed liver and adipose tissue." (PMID 39509324, 2024). "The overexpression of galectin-3 (Gal-3) has been described in a variety of cancers and is associated with tumor growth and metastasis." (PMID 39432076, 2024). "Galectin-3, a lactose-binding protein involved in various cellular processes, has been associated with increased tumor cell migration, invasion, and treatment resistance." (PMID 39451592, 2024). "Immunohistochemically, the tumor cells are positive for galectin-3 and E-cadherin, molecules that are implicated in abnormalities of tumor cell–stroma adhesion." (PMID 38672619, 2024). "In the TCGA database, LGALS3 was highly expressed in tumor groups, and high expression of LGALS3 was associated with poor prognosis in LUAD patients." (PMID 37265698, 2023). "These cells also differentially express Lgals3 that encodes Galectin 3, which in the tumor microenvironment has been shown attenuate T cell infiltration by capturing Ifng25." (PMID 37620372, 2023). "NKp30 ligands include B7-H6 and the HLA-B-associated transcript 3 protein (BAT3), also known as BAG6, both able to promote NK cell cytotoxicity against tumor cells and soluble galectin-3 implicated in NK cell tumor evasion." (PMID 37313439, 2023). "Consistently, knock-down of the galectin-3 gene was associated with the inhibition of cell migration, invasion, cell proliferation, colony formation and tumor growth in nude mice." (PMID 36873388, 2023). "LGALS1/GAL1 and LGALS3/GAL3 are β-galactoside–binding lectins and components of the tumor-associated bulky glycocalyx that regulate the function and structure of glycoproteins." (PMID 36735782, 2023). "Another member of this family, galectin-3 (Gal-3), is a tumor-associated protein present in the seminal fluid and is a substrate for the PSA enzyme." (PMID 35681683, 2022). "In our work, for the first time we have shown the association of reduced LGALS3 gene expression in the tumor with a distant metastasis in GC." (PMID 36430322, 2022). "As such, levels of galectin-3 have been especially implicated as an emerging biomarker for neoplasms." (PMID 35681762, 2022). "One of the pathways of malignant transformation and tumor progression is associated with changes in the expression of molecules, such as extracellular galectin-3 (Gal-3), and its binding to other molecules, leading to a process of tumor growth stimulation." (PMID 35886983, 2022). "High expression levels of Galectin 3 and EpCAM are associated with poor patient survival rates and a higher metastatic disease burden in all tumor types of this study." (PMID 35337112, 2022). "Serum galectin-3 has been proposed as an early marker of chronic inflammatory states associated with fibrosis, and of metabolic diseases and neoplasms." (PMID 34439802, 2021).
tumor (continued). "It was shown that down-regulation of galectin-3 and the other proteins were associated with decreased migration, invasion and reduced tumor growth." (PMID 34257527, 2021). "As with galectin-1, the expression levels of galectin-3 are higher in the more invasive sections of the tumor and the cells associated with peripheral vessels." (PMID 35008740, 2021). "LAG-3 also interacts with galectin-3 (GAL3) and liver sinusoidal endothelial cell lectin expressed on tumour cells and tumour-associated stromal cells, respectively." (PMID 33921181, 2021). "The lectin, galectin-3 (Gal3), has been implicated in a variety of inflammatory and oncogenic processes, including tumor growth, invasion, and metastasis." (PMID 33580170, 2021). "Genes associated with TEff/EMs such as Lgals3, GzmB, and Maf were preferentially expressed in both TEff/EMs and TRMs within the tumor environment." (PMID 33979626, 2021). "The galectin-3 molecule is secreted by inflammatory cells, and has been associated with tumour progression and metastasis in melanoma." (PMID 34441278, 2021). "LGALS3, which encodes the Galectin-3 protein, is regarded as a guardian of the tumor microenvironment." (PMID 32849813, 2020). "Although Lgals3 and Lgals3bp have been principally linked to tumor aggressiveness and metastasis, previous findings have suggested Lgals3 role in macrophage recruitment." (PMID 33257747, 2020). "Galectin-3 has also been implicated in tumour progression and metastasis in a variety of human cancers, such as thyroid, pancreas and breast carcinomas." (PMID 31652641, 2019). "In line with previous findings, strong cytoplasmic expression of galectin-3 was associated with later phases of tumor progression and was inversely correlated with the survival of patients." (PMID 29389859, 2018). "A soluble NG2/CSPG4 fragment released from tumor cells or tumor-associated pericytes can stimulate endothelial cell migration in the tumor microenvironment by interacting with galectin-3 and α3β1 integrin on the endothelial surface." (PMID 30213051, 2018). "Evidence suggests that the addition of sialic acid in the α2,6-position to the core 1 structure inhibits the cells' ability to bind to galectin-3, a lectin associated with many processes involved in tumour progression and metastasis." (PMID 29903935, 2018). "Accumulating data have demonstrated that different galectin-3 expression in tumor tissues was associated with unfavorable survival in cancer patients." (PMID 30410421, 2018). "We know that not only high expressions of MMPs and CD147 are associated with tumor invasion, but also high expression of tumoral galectin-3 was associated with tumor size and poor differentiation but negatively related to low E-cadherin expression." (PMID 29875690, 2018). "Galectin-3 is associated with tumor immune tolerance and exhibits an ability to induce T cell apoptosis." (PMID 28548942, 2017). "The resulting multivalent LacNAc type 1 presenting neo-glycoproteins were further studied for specific binding of the tumor-associated human galectin 3 (Gal-3) and its truncated counterpart Gal-3∆ in an enzyme-linked lectin assay (ELLA)." (PMID 28796164, 2017). "LGALS3 is a lectin protein that is abundantly secreted by tumor cells and tumor-associated macrophages." (PMID 28881848, 2017). "Galectin-3 (Gal3) plays diverse roles in cancer initiation, progression, and drug resistance depending on tumor type characteristics that are also associated with cancer stem cells (CSCs)." (PMID 27687248, 2016). "Initially, we evaluated the susceptibility of Lgals3+/+ or Lgals3 −/− female mice to 4T1 cells tumor growth." (PMID 27526676, 2016). "Tumor-associated macrophages, which express galectin-3, have been shown to act in tumor angiogenesis and vessel maturation in a density- and phenotype-dependent manner." (PMID 27242966, 2016).
tumor (continued). "Both galectin-1 and galectin-3 interact with oncogenic Ras, a proto-oncogene known to be mutated and constantly expressed in tumor cells rendering these two galectins to be favorable targets for therapy." (PMID 25730388, 2015). "Based on the increased expression of Arginase I in WTG3 tumors, as well as on the notion that tumor-associated macrophages are polarized to the protumorigenic M2 phenotype, we next tested the impact of galectin-3 disruption in this phenomenon." (PMID 24421272, 2014). "The Galectin-3 molecule is mainly secreted by inflammatory cells and is associated with both tumor progression and metastasis in melanoma." (PMID 25667918, 2014). "Galectin-3, one of the most studied members, is commonly up or down regulated in different cancers and is implicated in tumor formation and proliferation, apoptosis, angiogenesis, and B cell activation." (PMID 25161713, 2014). "Different groups have suggested that galectin-3 plays a role in controlling tumor-associated angiogenesis." (PMID 24421272, 2014). "Galectin-3 also seems to be involved in the recruitment of tumor-associated macrophages, possibly contributing to angiogenesis and tumor growth." (PMID 24982845, 2014). "Galectin-3 is a multifunctional protein implicated in various biological functions, including: the adhesion, proliferation and differentiation of tumor cells, angiogenesis, cancer progression and metastasis." (PMID 25260879, 2014). "Increasing evidence has shown that galectin-3 is implicated in the modulation of growth of tumor cells." (PMID 25260879, 2014). "In the multivariate analysis, we observed that galectin-3 expression, together with some traditional prognostic factors (tumor size, histologic grade) were independent risk factors in the prognosis of HCC patients." (PMID 25260879, 2014). "Galectin-3 is a tumor-associated protein; present in the seminal fluid and is a substrate for the PSA enzyme e.g., a chymotrypsin-like serine protease." (PMID 23625538, 2013). "We and others have observed an overexpression of either galectin-1 or galectin-3 in tumour-associated ECs." (PMID 23799140, 2013). "Increased expression of galectin-1 and/or galectin-3 has been reported to be associated with tumour progression." (PMID 23799140, 2013). "al. provide clear evidence for an effect of galectin-3 on cell migration and invasion, properties associated with tumor progression." (PMID 22900040, 2012). "Later investigations showed that galectin-3 expression was positively associated with tumor keratinization and histologic grade." (PMID 23658855, 2010). "Macrophages expressing galectin-3 are driven towards the alternative pathway of activation, usually associated with the M2 phenotype, which favours tumour growth and angiogenesis." (PMID 20465821, 2010). "Low levels of galectin-3 expression in the tumour epithelium are associated with significantly better prognoses than those characterized by high levels." (PMID 21339979, 2010). "Lgals3 (lectin) has been demonstrated to be associated with assorted processes such as cell growth, tumor transformation and metastasis." (PMID 17118139, 2006). "Additionally, in the cancer context, LAG-3 also binds fibrogen-like protein 1 (FGL1) released by cancer cells, galectin-3 on tumor and tumor-associated stroma cells, and LSECtin on tumor cells." (PMID 40075753, 2025). "Second, we evaluated the prognostic relevance of LGALS3 across diverse cancer types using pan-cancer datasets from The Cancer Genome Atlas (TCGA), examining its association with overall survival in multivariable models adjusted for tumor stage and purity." (PMID 41153387, 2025). "The most abundant checkpoint ligand in terms of both absolute expression levels as well as being expressed by tumour cells and by different types of infiltrating myeloid cells is Lgals3/LGALS3, encoding GALECTIN-3, a ligand for the LAG-3 immune checkpoint receptor." (PMID 40473819, 2025).
tumor (continued). "Meanwhile, the expression of LGALS3 within HCC was significantly associated with the advanced tumor stage and grade, indicating that elevated LGALS3 expression could increase tumor progression." (PMID 38643145, 2024). "A study has indicated that Galectin-3, a protein expressed in both tumor cells and Cancer-Associated Fibroblasts (CAFs), might exert a substantial influence on tumor progression and cell surface polarity." (PMID 38181281, 2024). "Additionally, we evaluate galectin-3 expression in invasive regions with a focus on tumor budding areas and investigate its association with critical prognostic parameters such as tumor stage and histological grade." (PMID 39451592, 2024). "While the exact source of galectin-3 (tumor cells versus the microenvironment) remains unclear, its expression has been associated with hypoxic regions within the tumor." (PMID 38732975, 2024). "LGALS3 is secreted by many tumor cells and associated with neoplastic transformation." (PMID 37215135, 2023). "The PDAC tumor cells promote galectin-3 expression, reduce infiltration of associated lymphocytes, adapt to the tumor microenvironment under conditions of hypoxia and starvation, and promote further tumor cell development." (PMID 36428567, 2022). "Additional findings illustrated that cytoplasmic galectin-3 was associated with tumor progression." (PMID 36713574, 2022). "Indeed, blocking galectin-3 in a murine tumor model increased CD8+ T cell infiltration, which was linked to an increase in IFN-γ mediated chemokine expression." (PMID 36139125, 2022). "When looking at the Leiden 64-case cohort, expression of Galectin-3 (p = 0.002), one of the probes for HLA-DRalpha (p = 0.02), HLA-DQbeta2 (p = 0.02) and HLA-DPalpha (p = 0.01) was significantly higher in high-risk M3 tumours compared with low-risk D3 tumours." (PMID 34503258, 2021). "Previous reports showed that MMP and Galectin-3 expression and function may interfere with tumor associated NK cell cytotoxicity." (PMID 34066355, 2021). "Lgals3 encodes galectin-3 (Gal-3), a lectin involved in tumor immunosuppression." (PMID 33608526, 2021). "It has also been reported that EMT inducer factors such as TGF-β1, PGE2, indoleamine 2,3-dioxygenase, sMICA, and LGALS3 are produced by a variety of immune suppressor cells like tumor-associated fibroblasts, Tregs, MDSCs and even tumor cells attenuated NK cell-mediated cytotoxicity." (PMID 33129234, 2021). "They used both genetic and pharmacologic inhibition of Galectin-3 in vivo and in vitro to identify underlying mechanisms and define a Galectin-3/macropinocytosis molecular signature, which could inform the development of anti-tumour therapeutic strategies." (PMID 34112916, 2021). "This would suggest that galectin-3 may not only be valuable in staging a tumor, but also in evaluating its susceptibility to chemotherapy." (PMID 32033052, 2020). "As reported by the author, galectin 3 levels were strictly associated with tumor suppression." (PMID 32859099, 2020). "Moreover, in vivo studies demonstrated that LGALS3 deficiency was significantly associated with a smaller tumor burden, less invasive characteristics, reduced proliferation and an increased apoptosis rate, while rLGALS3 showed the opposite effects." (PMID 32564007, 2020). "Galectin-3 (Gal-3), a member of β-galactoside-binding lectins, is a chimeric glycoprotein encoded by a single gene, LGALS3, in humans, and plays multiple roles in cancer initiation, adhesion, progression, metastasis, angiogenesis, and adaptation in tumor microenvironments." (PMID 32630393, 2020). "Since galectin-1 and galectin-3 are implicated in the increased angiogenesis that drives tumor proliferation and expansion, monoclonal antibodies against these galectins could help mitigate the VEGF pathway and slow cancer progression." (PMID 32033052, 2020). "Furthermore, the tumor-endothelial cell interactions required for metastasis are believed to be mediated by endothelium-associated galectin-3." (PMID 32190664, 2020).